ERBB2 (erb-b2 receptor tyrosine kinase 2)
Diseases named in the same sentence as ERBB2 in open-access papers (continued):
Sharing a sentence is not in itself a finding about the gene and the disease.
ovarian carcinoma (continued). "Selumetinib added to saracatinib overcomes the EGFR/HER2/ERBB2–mediated bypass activation of MEK/MAPK that is observed with saracatinib alone and targets tumor-initiating ovarian cancer populations, supporting combined Src–MEK inhibition therapeutics for future trials." (PMID 31547471, 2019). "No ERBB2 genomic alterations were found in prostate cancers (n = 54), ovarian cancers (n = 37) or sarcomas (n = 49)." (PMID 29515767, 2018). "Also, downregulation of miR-199a resulted in high expression of ERBB2 and ERBB3 in ovarian cancer cells and promoted cancer progression." (PMID 28978024, 2017). "Also, a recent clinical study agrees with our finding, showing that lapatinib had a minimal activity and only a small fraction of ovarian cancer overexpressed EGFR and ERBB2 (HER2)." (PMID 27558154, 2016). "In either case, selection of ERBB2 inhibitor for treatment of ovarian cancer should not be based solely on its level of gene expression." (PMID 27558154, 2016). "Similar to first generation CARs, several different scFvs have been used with second generation CARs including EpCAM for multiple carcinomas including breast and ovarian cancer, an HLA-A2 EBNA3C complex for Epstein–Barr virus, CS1 for MM, and ErbB2 for HER2 positive cancers." (PMID 25972867, 2015). "The receptor tyrosine kinases (RTKs), including EGFR, ERBB2, PDGFR, VEGFR and MET, are activated in subsets of ovarian cancer, suggesting that these kinases might represent novel therapeutic targets." (PMID 21962244, 2011). "Integrative bioinformatics of cisplatin-treated ovarian cancer datasets from the Gene Expression Omnibus (n=255) identified six molecular drivers of resistance: Kaiso (ZBTB33), pregnane X receptor (PXR), NF-κB, HER2 (ERBB2), P-glycoprotein (P-gp/ABCB1), and HIF1A." (PMID 41438580, 2026). "In addition to MUC1 and HER2 (ErbB2), CEA is also overexpressed in both BC and ovarian cancer (OC)." (PMID 40333213, 2025). "Cross-sectional cohort analysis of serum samples using the ExoCounter system showed a significant rise in receptor tyrosine-protein kinase erbB-2 (HER2)-positive exosomes in patients with breast or ovarian cancer compared to healthy individuals and patients without cancer." (PMID 38689293, 2024). "Because ErbB2 was reported to be expressed in chondrocytes and GDF15 was observed to interact with this receptor in ovarian cancer, we demonstrated that this interaction was conserved in chondrocytes and may have partially explained the mechanism of the GDF15/MAPK14 signaling pathway." (PMID 35806043, 2022). "The implications of oncogene expression on cancer drug resistance remain poorly understood, although there have been over 25 oncogenes including KRAS, ERBB2, PIK3CA, AKT hypothesized to contribute to drug resistance in ovarian cancer through various signalling pathways." (PMID 35545786, 2022). "This includes ERBB2/HER2 amplification in endometrial carcinoma, renal papillary carcinoma, testicular germ cell tumors, urothelial carcinoma, renal clear cell carcinoma, colon carcinoma, ovarian carcinoma, thymoma, thyroid carcinoma, cervical carcinoma, and head and neck squamous cell carcinoma." (PMID 30442178, 2018). "Collectively, these results show that ErbB2 and ErbB3 control basal, constitutively active levels of pAkt and down regulation of ErbB2 and ErbB3 contributes to α-TEA-induced suppression of pAkt and induction of apoptosis in both A2780S and A2780/CP70R human ovarian cancer cells." (PMID 20224651, 2010). "ERBB2 expression has been found in 19 to 44% of ovarian carcinomas; however, its predictive value has not been demonstrated, and trastuzumab has not found clinical application in ovarian cancer patients." (PMID 15545967, 2004).
ovarian carcinoma (continued). "However, there are also studies showing that serum VEGF levels might be used for diagnosis in ovarian cancer patients, while serum ErbB2 levels do not have a clinical significance in terms of ovarian cancer." (PMID 29482638, 2018). "This suggests that while ERBB2 may be overexpressed in OCCC on the mRNA level relative to other histological subtypes of ovarian cancer, this does not result in overexpression on the protein level, nor does it appear to be caused by amplification of the ERBB2 gene." (PMID 28611940, 2017). "We show that its synergistic anti-cancer effect, when combined with paclitaxel, is independent of EGFR, ERBB2, or ERBB4 antagonism in human ovarian cancer cell models." (PMID 34347777, 2021). "This region is amplified in numerous ovarian cancer cell lines including OVCAR-3, OVCAR-5, OVCAR-8, and CAOV-3 and in a small population of ovarian tumors, although targeting Her2 (ERBB2) has not been successful to date in EOC." (PMID 21781307, 2011). "However, clinical trials have not or just partially shown benefit to ovarian cancers treated with EGFR, ERBB2, or PDGFR inhibitors." (PMID 21962244, 2011).
lung cancer (864 papers, 2002 to 2026). A malignant neoplasm involving the lung. "In the last 2 years, T-DXd was approved to treat non–small cell lung cancer (NSCLC) with select ERBB2 mutations, and tucatinib plus trastuzumab was approved to treat HER2 amplification and/or overexpression in colorectal cancer (CRC)." (PMID 40178042, 2025). "Patients with advanced lung cancer with the ERBB2 mutation have previously been reported to have a poor prognosis." (PMID 41154672, 2025). "HER2 ex20ins include Y772_A775dup, G778_P780dup, and G776delinsVC, and are observed in nearly 90% of ERBB2-mutated lung cancers." (PMID 41154672, 2025). "HER2 mutations occur in 2–4% of cases, and amplifications in 1–3% Mutations in the HER2 (ERBB2) gene define a distinct molecular subtype of lung cancer, primarily found in adenocarcinomas, with higher prevalence among women and non-smokers." (PMID 40526089, 2025). "In lung cancers with amplifying or mutated ERBB2, ado-trastuzumab emtansine (T-DM1) was also validated in the PDX model before becoming the first ADC approved in China." (PMID 36911198, 2023). "PIK3CA and ErbB2 gene co-variation most associated with primary EGFR-TKIs resistance in EGFR-mutant lung cancer patients." (PMID 37553597, 2023). "ERBB2 exon 16 skipping is also reported to be another mechanism of TKI resistance in EGFR-mutated patients with lung cancer, in addition to its role in other solid malignancies as an oncogenic driver." (PMID 35463314, 2022). "On the other side, although no targeted drugs are approved for ERBB2-mutated cancers by far, several clinical trials have exhibited promising results in lung cancer patients carrying ERBB2 mutations." (PMID 35911441, 2022). "In contrast, patients with ERBB2 mutation had lower TMB compared with non-ERBB2 mutation in lung cancer (p = 0.048)." (PMID 35911441, 2022). "Lung cancer organoids with an ALK1 mutation were shown to be resistant to crizotinib whereas ERBB2 mutated cancer organoids were sensitive to erlotinib and gefitinib." (PMID 33816288, 2021). "Our study provided valuable insights into the distribution of ERBB2 TMD mutations by employing the largest Asian lung cancer cohort thus far." (PMID 32478891, 2020). "Our study provides valuable insights into the distribution of ERBB2 TMD mutations by employing the largest Asian lung cancer cohort thus far." (PMID 32478891, 2020). "Transmembrane domain (TMD) mutations of ERBB2 were identified in 0.13% of a large Chinese lung cancer cohort with a ratio of 0.17% in lung adenocarcinomas." (PMID 32478891, 2020). "In lung cancer, most of the ERBB2 β3‐αC mutations are point mutations and the percentage of drug‐relevant mutations was 59% (10/17)." (PMID 32757330, 2020). "Our analysis revealed that ERBB2 TMD mutation accounted for 0.13% of all lung cancer cases, which was extremely rare and majority were restricted to lung ADC." (PMID 32478891, 2020). "Investigation of the transcriptome profiles modified by Erbb2 loss during lung cancer development can help us to understand the molecular impact of ERBB2 on lung tumor formation." (PMID 31248101, 2019). "ERBB2 is an oncogenic driver with frequent gene mutations and amplification in human lung tumors and is an attractive target for lung cancer therapy." (PMID 31248101, 2019). "PI3KCA activating mutations were associated with ERBB2 mutations in 12.4% of cases mainly in breast and lung cancer." (PMID 29941010, 2018). "With the use of this two-tier strategy, we reliably determined the frequency of EGFR mutations and EGFR, MET and ERBB2 amplifications in over 200 lung cancer samples." (PMID 25719557, 2015). "One example is the utility of human EGFR 2 (HER2)-directed treatments for patients with lung cancer that have a HER2 (encoded by the ERBB2 gene) mutation." (PMID 24782778, 2014).
lung cancer (continued). "Others have shown that non-hotspot KRAS and NRAS mutations occurring in leukemias and rare ERBB2 mutations in lung cancer are functionally transforming." (PMID 23237847, 2013). "Preclinical activity for afatinib (BIBW2992), a second irreversible inhibitor of EGFR and ERBB2, was demonstrated in Ba/F3 cells expressing an ERBB2-mutant with an insertional mutation at codon 776 and in transgenic lung cancer models." (PMID 23630663, 2013). "A recent paper showed that the p14/ARF protein was frequently down regulated in lung cancers with EGFR mutation or in tumors with ERBB2 mutations." (PMID 18549475, 2008). "For instance, both mutation and high amplification could be detected in EGFR, MET, and ERBB2 in lung cancer, as well as mutations in KRAS, BRAF, STK11, KEAP1 and many others." (PMID 39289779, 2024). "The overexpression of ERBB2 is associated with very aggressive breast and drug-resistant lung cancer because ERBB2 is a membrane protein that signals and amplifies for proliferation, pro-survival, and prometastatic signals of the cancer leading to poor clinical outcomes." (PMID 37359373, 2023). "To explore whether GEMINI could be used to monitor patients during therapy, we assessed serial blood samples from patients with lung cancer who were undergoing treatment with EGFR or ERBB2 inhibitors with mutant allele fractions (MAFs) as low as 0.1%." (PMID 37500728, 2023). "Furthermore, among the differentially methylated blocks identified, 1 block covered the gene promoter of ERBB2, which is closely related to lung cancer and whose loss of function affects the expression of cell cycle and pro-apoptotic genes." (PMID 34952628, 2021). "The most common ERBB2 mutations were the KD mutations at 2.3% (802 out of 34 368), followed by extracellular domain mutations (1.0%, 340 out of 34 368), which were identified in multiple subtypes of lung cancer." (PMID 32478891, 2020). "Another study suggested that the Ala variant increased the risk of lung cancer, indicating that it may promote ERBB2 activity." (PMID 32332709, 2020). "While the prevalence of ERBB2 amplification was higher in patients with GI cancers (P = 0.013), no exon 20 insertion mutations were observed in that subset of patients but rather were exclusively identified in patients with lung cancer." (PMID 31019892, 2019). "Therefore, more studies are needed to understand the underlying mechanism of ERBB2-regulated lung cancer development." (PMID 31248101, 2019). "Similarly, the inhibitory effect of the CHRNA9/ERBB2 complex disassociation and signal transduction caused by bupropion were also found in lung cancer (A549) cells exposed to nicotine." (PMID 31311925, 2019). "In addition to amplification, mutations have been described in ERBB2 that occur at low frequency in several tumor types, especially in breast (3%), colon (2-3%) and lung cancers (1-2%)." (PMID 29515767, 2018). "Whereas non–small cell lung cancer represented the highest proportion of ERBB2-mutated (i.e., single-nucleotide variants and short insertions/deletions) cancers (19.0%), breast, colorectal, bladder, and gastroesophageal cancers combined accounted for 50.4% of ERBB2-mutated tumors." (PMID 40178042, 2025). "In addition, the close structural similarity of exon 20 of EGFR and receptor tyrosine-protein kinase erbB-2 (ERBB2) indicates that our findings could be applicable to ERBB2 mutated lung cancer." (PMID 34944068, 2021). "Another patient with ERBB2 IHC (1+) was found with an ERBB2-P780_Y781insGSP mutation, the third most common HER2 exon 20 insertions in lung cancer, which indicated that anti-Her2 therapies such as neratinib and trastuzumab ado-trastuzumab emtansine (T-DM1) might benefit patients." (PMID 34396843, 2021).
lung cancer (continued). "Transmembrane domain (TMD) mutations of ERBB2 have previously been reported in lung cancer patients in addition to well‐studied kinase domain (KD) mutations, which may stabilize ERBB2 heterodimerization with other EGFR family members and favor a kinase active conformation." (PMID 32478891, 2020). "Recently, ERBB2 mutations, especially in exon 19 and 20, have emerged as a clear target for HER2-targeting therapies such as ADCs and TKIs in lung cancer." (PMID 41154672, 2025). "In conclusion, this case report highlights the promising potential of Enhertu as a treatment for lung cancer patients with ERBB2 mutations and HER2 overexpression, particularly in the context of recurrent brain metastasis." (PMID 41180730, 2025). "According to the TCGA database, 9% of lung cancer patients harbor EGFR mutations, while 2% exhibit ERBB2 mutations." (PMID 39596025, 2024). "The management of lung cancer (LC) requires the analysis of a diverse spectrum of molecular targets, including kinase activating mutations in EGFR, ERBB2 (HER2), BRAF and MET oncogenes, KRAS G12C substitutions, and ALK, ROS1, RET and NTRK1-3 gene fusions." (PMID 38966170, 2024). "We explored if the treatment with the novel engineered destabilized 3'UTR of ERBB2 inhibited the lung cancer metastasis." (PMID 38699639, 2024). "Cohort studies have demonstrated that GERD is a significant risk factor for EGFR-mutant lung cancer, and acid bile salt mimics GERD exposure and enhances ERBB2-mediated activation of immune cell/inflammatory pathways." (PMID 38414734, 2024). "Approximately 1% of lung carcinomas demonstrate amplification and overexpression of ERBB2 (HER2) oncogene." (PMID 38966170, 2024). "A study of feline lung carcinomas found HER2 protein overexpression (by IHC) in 15% of cases and ERBB2 gene amplification in 27% of cases." (PMID 38787171, 2024). "Non‐small cell lung cancers with ERBB2 amplification, MET activation, KRAS G12C, RET, and ROS1 fusion resulted in the second‐highest frequency of recommendations." (PMID 36251535, 2023). "Seemingly consistent with this finding, chromothripsis is frequently detected in lung cancers driven by EGFR mutations, and mutation of EGFR and ERBB2 is associated with more rearrangement events in LUADs." (PMID 36761982, 2023). "TKIs targeting ERBB2 have limited activity in patients with ERBB2-positive tumors, although some case series have reported that lung cancer patients with ERBB2 20ins can benefit from TKIs, such as afatinib and poziotinib." (PMID 37767514, 2023). "Many studies have shown that, as important genes constituting the ERBB network, EGFR and ERBB2 (20ins) are significantly related to the development and invasion of lung cancer." (PMID 36816028, 2023). "We constructed a CCCN and CFN from measurements of phosphorylation, acetylation, and ubiquitination in 10 different lung cancer cell lines with driver mutations in EGFR, ALK, ERBB2/HER2, ROS1, and DDR2, treated with four different TKIs." (PMID 36996232, 2023). "Resistance to trastuzumab and other tyrosine kinase inhibitors in ERBB2+ breast and lung cancer is a grand challenge that needs to be overcome to improve clinical outcomes and to prevent drug resistance and help sufferers of these deadly cancers." (PMID 37359373, 2023). "Some researchers have revealed that propofol restrained cell malignant phenotypes via downregulating FOXM1 through regulating the circ_RHOT1/miR-326 axis in NSCLC and the circ_TADA2A/miR-155-3p axis or circ_ERBB2/miR-7-5p axis in lung cancer." (PMID 36760719, 2023). "For instance, propofol restrained tumorigenesis through downregulation of circ_PVT1 in gastric cancer, circ_TADA2A and circ_ERBB2 in lung cancer, and circ_VPS13C in ovarian cancer." (PMID 36760719, 2023). "Exon 20 (ex20) in-frame insertions or duplications (ins/dup) in epidermal growth factor receptor (EGFR) and its analog erb-b2 receptor tyrosine kinase 2 (ERBB2) are each detected in 1.5% of non–small cell lung cancer (NSCLC)." (PMID 37284196, 2023).